ZNF490 (zinc finger protein 490)
Description:
May be involved in transcriptional regulation.
Synonyms: KIAA1198
Tractability: PROTAC: ubiquitination databases record sites on it.
Gene: Protein-coding gene on chromosome 19 (12,576,100 to 12,640,098, reverse strand). Ensembl gene ENSG00000188033.
Subcellular location: Nucleus
Pathways (Reactome):
Gene expression (Transcription): Generic Transcription Pathway
Gene Ontology:
Molecular function: protein binding; DNA-binding transcription factor activity, RNA polymerase II-specific; RNA polymerase II cis-regulatory region sequence-specific DNA binding
Biological process: regulation of transcription by RNA polymerase II; regulation of DNA-templated transcription
Cellular component: nucleus
Genetic constraint (gnomAD): Loss-of-function variants: 9 observed, 17 expected, observed/expected ratio (o/e) 0.53, 90% interval 0.32 to 0.92. The upper end of that interval is the gene's LOEUF score, 0.92, which puts it in group 3 of 6, group 1 being the genes least tolerant of losing a copy. Missense variants: 540 observed, 672.83 expected, observed/expected ratio (o/e) 0.8, 90% interval 0.75 to 0.86. Synonymous variants: 222 observed, 227.1 expected, observed/expected ratio (o/e) 0.98, 90% interval 0.88 to 1.09.
Homologues: Orthologues: chimpanzee ZNF490 (100% identical), macaque ZNF490 (97% identical). Paralogues in human: ZNF699 (45% identical), ZNF33B (45% identical), ZNF708 (45% identical), ZNF568 (44% identical), ZNF41 (44% identical), ZFP28 (44% identical), ZNF227 (44% identical), ZNF595 (43% identical), ZNF30 (43% identical), ZNF658 (43% identical), ZNF726 (43% identical), ZNF7 (43% identical), and 164 more.
Diseases named in the same sentence as ZNF490 in open-access papers:
ZNF490 is named in the same sentence as 4 diseases in open-access papers, as found by Europe PMC text mining. Sharing a sentence is not in itself a finding about the gene and the disease. The quoted sentences say what the papers report.
bipolar disorder (1 paper, 2013). A disorder of the brain that causes unusual shifts in mood, energy, activity levels and the ability to carry out day-to-day tasks. "Finally, the 3′UTR SNP rs7247513 (ZNF490 gene), modestly associated with bipolar disorder (P-value = 2E-6), was also found in high LD with a 2 kb deletion covering ZNF490 intron." (PMID 23844243, 2013).
melanoma (1 paper, 2018). A malignant, usually aggressive tumor composed of atypical, neoplastic melanocytes. "Moreover, genes showing hypermethylation in melanoma such as KRTCAP3, AGAP2, ZNF490, and TTC22 were newly recognized in the present study." (PMID 30719424, 2018). "Furthermore, expression of AGAP2, ZNF490, and TTC22 was not decreased in melanoma (data not shown)." (PMID 30719424, 2018).
cancer (2 papers, 2013 to 2021). A tumor composed of atypical neoplastic, often pleomorphic cells that invade other tissues. "The following genes displayed LOH in at least one cancer: UACA, TWSG1, PSPH, and ZNF490." (PMID 24146633, 2013).
ZNF490 also shares sentences with these, for which no sentence is quoted: tumor (1 paper).